NCS1 (neuronal calcium sensor 1)
Diseases named in the same sentence as NCS1 in open-access papers (continued):
Sharing a sentence is not in itself a finding about the gene and the disease.
breast carcinoma (continued). "We demonstrated the relevance of these in vitro findings for human breast cancer through analysis of human RNA expression data, which showed the activation of NFκB signaling in breast cancer tissue in concordance with NCS1 up‐regulation." (PMID 32239615, 2020). "We found that NCS‐1 expression is also significantly higher in the basal molecular subtype compared to other breast cancer subtypes." (PMID 31647602, 2020). "Silencing NCS‐1 enhanced doxorubicin‐induced breast cancer cell death, which was a phenomenon phenocopied by the silencing of the Ca2+ store refilling channel ORAI1." (PMID 31647602, 2020). "An alternative explanation is that basal breast cancer cells with elevated NCS‐1 have an upregulation of unstimulated basal Ca2+ influx, perhaps to maintain ER Ca2+ store levels or via another mechanism." (PMID 31647602, 2020). "Having determined that NFκB signaling and NCS1 are altered in human breast cancer, we moved to investigate the specific role of NCS1 in breast cancer." (PMID 32239615, 2020). "Given the ability of NCS‐1 silencing to phenocopy the effects of ORAI1 silencing in MDA‐MB‐231 breast cancer cells, we explored the possibility that NCS‐1 silencing‐mediated suppression of unstimulated Ca2+ influx was due to reduced expression of ORAI1." (PMID 31647602, 2020). "We also observed a trend toward increased NCS‐1 expression in basal breast cancer cell lines compared to HER2 and luminal breast cancer cell lines." (PMID 31647602, 2020). "We also observed that higher levels of NCS‐1 predict poorer survival within the basal molecular breast cancer subtype." (PMID 31647602, 2020). "Here, we report for the first time that NCS‐1 expression is increased in the basal breast cancer molecular subtype." (PMID 31647602, 2020). "More recently, NCS‐1 was shown to play a role in breast cancer invasion and migration in vitro, and higher NCS‐1 expression correlates with poorer survival in breast cancer patients." (PMID 31647602, 2020). "Our study is the first to identify an association between NCS‐1 and unstimulated basal Ca2+ influx in breast cancer cells and comprehensively characterize the role of NCS‐1 in Ca2+ homeostasis in breast cancer cells." (PMID 31647602, 2020). "This work provides further insight into the role of NCS‐1 in modulating therapeutic responses in basal breast cancer." (PMID 31647602, 2020). "Further association between NCS‐1 and ORAI1 was seen in breast cancer samples where a positive correlation was observed between these two genes." (PMID 31647602, 2020). "We found that this mechanism of NCS1 up‐regulation is conserved in the pathophysiology of human breast cancer, and we showed that NCS1 has essential functions for cell survival and migration through altering intracellular Ca2+ signaling and Akt signaling." (PMID 32239615, 2020). "Collectively, these results identify a critical role for NCS‐1 in modulating unstimulated Ca2+ influx likely through ORAI1 channels, since ORAI1 silencing phenocopied the effect of NCS‐1 silencing in GCaMP6m‐MDA‐MB‐231 breast cancer cells." (PMID 31647602, 2020). "Further studies characterizing the role of NCS‐1 in specific intracellular Ca2+ and survival signaling pathways and in other basal breast cancer cell lines are now warranted." (PMID 31647602, 2020). "We found that NFκB signaling is activated in human breast cancer tissue, which was accompanied by an increase in NCS1 mRNA expression." (PMID 32239615, 2020). "Hierarchical clustering of NCS‐1 and breast cancer molecular markers showed a positive correlation with basal and proliferative markers, such as KRT5, 14 and 17, CDH3, FOXC1, FOXM1, EGFR, and MKI67." (PMID 31647602, 2020). "Here, we assess NCS-1 expression in a retrospective collection of breast cancer patients treated with neoadjuvant therapy to assess its predictive value." (PMID 29560416, 2018).
breast carcinoma (continued). "Moreover, APOL3 has been found to regulate neuronal calcium sensor 1 (NCS-1), which plays a critical role in promoting the metastasis and survival of breast cancer cells in vitro." (PMID 38067270, 2023). "The effect of NCS‐1 silencing on cell death was phenocopied by silencing of ORAI1, a Ca2+ store‐operated Ca2+ channel that maintains Ca2+ levels in the endoplasmic reticulum Ca2+ store and whose expression was significantly positively correlated with NCS‐1 in clinical breast cancer samples." (PMID 31647602, 2020). "In this study, we report for the first time that NCS‐1 is more highly expressed in the basal molecular subtype, a subtype which has a strong overlap with TNBC and is associated with poorer survival rates in breast cancer patients." (PMID 31647602, 2020). "Neuronal calcium sensor‐1 (NCS‐1) expression is higher in basal breast cancers." (PMID 31647602, 2020). "Despite the recently reported association between NCS‐1 and increased breast cancer invasion and migration, the role of NCS‐1 in Ca2+ signaling in breast cancer cells has not been reported." (PMID 31647602, 2020). "Furthermore, we found that NCS1 expression was significantly higher in breast cancer samples compared to normal breast samples." (PMID 32239615, 2020). "One such highly-upregulated (Hx/Nx >10) molecule in our dataset was the calcium-binding protein NCS1 (neuronal calcium sensor 1) which performs a variety of different functions in normal cell biology but has also been shown to promote metastasis in breast cancer." (PMID 31666928, 2019). "Finally, to assess if NCS‐1 expression had any association with patient survival in basal breast cancers, we used the Kaplan–Meier Plotter online tool to stratify the overall survival (OS) of breast cancer patients with basal tumors based on NCS‐1 gene expression." (PMID 31647602, 2020). "In addition, these results further support our hypothesis that NCS1‐dependent signaling has a specific function in breast cancer." (PMID 32239615, 2020). "In summary, our work shows the functional interaction between NCS-1 and TRPA1 in MDA-MB-231 cells, a breast cancer cell line, and SH-SY5Y cells, a neuronal model." (PMID 38564162, 2024). "According to the TMA data, the high expression of NCS1 was observed in KIRC (Kidney Clear Cell Carcinoma), SKCM (Melanoma), and BRCA (Breast Cancer)." (PMID 37893139, 2023). "We determined the importance of NCS1 for cell survival and migration using a model of breast cancer cells (MDA‐MB231) lacking NCS1 expression." (PMID 32239615, 2020). "Collectively, these data suggest that NCS‐1 is not a major regulator of ER Ca2+ release in MDA‐MB‐231 breast cancer cells." (PMID 31647602, 2020). "Higher NCS‐1 expression correlates with a poorer OS in the basal breast cancer patient subgroup (HR = 3.15, P = 0.0002), further implicating the significance of NCS‐1 in basal breast cancers." (PMID 31647602, 2020). "Using MDA‐MB‐231 basal breast cancer cells expressing the GCaMP6m Ca2+ indicator, we showed that NCS‐1 silencing did not result in major changes in cytosolic free Ca2+ increases as a result of endoplasmic reticulum Ca2+ store mobilization." (PMID 31647602, 2020). "Despite the involvement of NCS‐1 in regulating Ca2+ homeostasis and its association with breast cancer, no studies have assessed the role of NCS‐1 in intracellular Ca2+ signaling in breast cancer cells." (PMID 31647602, 2020). "However, there was no major change in IP3‐mediated Ca2+ signals with NCS‐1 silencing in MDA‐MB‐231 breast cancer cells." (PMID 31647602, 2020). "Likewise, lower levels of ORAI3 would indeed be predicted in the breast cancer cells with high levels of NCS‐1 since ORAI3 levels are found to be lower in basal breast cancers, which we have shown to have higher levels of NCS‐1." (PMID 31647602, 2020).
breast carcinoma (continued). "To investigate the relevance of TNF signaling via NFκB activation and NCS1 up‐regulation in human cancer, we analyzed the gene expression patterns of NFκB‐regulated genes and NCS1 expression in a dataset from an RNA microarray performed on human breast cancer and noncancerous breast tissue." (PMID 32239615, 2020). "Due to the role of NCS‐1 as a positive regulator of IP3Rs and the lack of studies defining a role for NCS‐1 in Ca2+ signaling in breast cancer cells, we assessed two possible consequences of NCS‐1 silencing in the GCaMP6m‐MDA‐MB‐231 breast cancer cell line." (PMID 31647602, 2020). "Assessment of the role of TRPM8, which was also positively correlated with NCS‐1, may be challenging given the absence of TRPM8 in many commonly used breast cancer cell lines." (PMID 31647602, 2020). "Collectively, these results demonstrate that NCS‐1 is not a major direct regulator of SOCE and that promotion of unstimulated Ca2+ influx may already be maximal in GCaMP6m‐MDA‐MB‐231 breast cancer cells." (PMID 31647602, 2020).
Anxiety (6 papers, 2016 to 2021). Intense feelings of nervousness, tension, or panic often arise in response to interpersonal stresses. "Interestingly, NCS-1-deficiency also resulted in anxiety- and depressive-like behaviors as demonstrated by elevated plus maze, large open field, forced swim and tail suspension tasks." (PMID 31001084, 2019). "NCS-1 deficiency also results in decreased levels of BDNF (present data) and causes anxiety and depressive-like behavior." (PMID 28122057, 2017). "Furthermore, NCS-1 deficits result in anxiety and depressive-like behavior, as well as impairments in non-aversive memory, in mice." (PMID 28122057, 2017). "Combining these data with the previously reported anxiety- and depressive-like behaviors of NCS-1−/− mice implicates NCS-1 in a relationship of diabetes type 2 and depression, frequently observed with human patients." (PMID 31001084, 2019). "Researchers have also reported that NCS-1 KO mice exhibit anxiety and depressive-like behavior, in addition to impaired non-aversive memory." (PMID 28122057, 2017).
neuroblastoma (6 papers, 2010 to 2024). Neuroblastoma (NB) is the most common solid, extracranial childhood tumor. "NCS‐1 interacts with IP3R and increases its opening probability, and NCS‐1 silencing reduces IP3‐mediated Ca2+ signals mediated by ATP in neuroblastoma cells and endothelin in cardiomyocytes." (PMID 31647602, 2020). "We therefore identified mouse N2A neuroblastoma cells as expressing both proteins, and characterised NCS-1 localisation in this cell line." (PMID 20479890, 2010). "After cloning NCS1 Var1 and NCS1 Var2 into the mammalian expression vector pcDNA 2.1/3.1, Western blots of transiently transfected SHSY5Y, a human neuroblastoma cell line, showed expression of two distinct bands representing the two isoforms." (PMID 27575489, 2016). "To test whether NCS1 is regulated by NFκB, we treated SHSY5Y human neuroblastoma cells with TNF‐α and consequently measured NCS1 protein expression." (PMID 32239615, 2020). "We initially screened a set of siRNAs targeting Ncs1 in mouse neuroblastoma Neuro2A cells and found one siRNA (Freq 3) reduced NCS-1 protein levels relative to the negative siRNA." (PMID 26639399, 2015).
autism spectrum disorder (5 papers, 2010 to 2021). A spectrum of developmental disorders that includes autism, and Asperger syndrome. "Mutations in IL1RAPL1 have recently been associated with autism spectrum disorders and a missense mutation (R102Q) on NCS-1 has been found in one individual with autism." (PMID 20479890, 2010).
neuropathy (5 papers, 2017 to 2025). A disorder affecting the nervous system that manifests with pain, tingling, numbness, and/or muscle weakness. "The role of neuronal calcium sensor-1 (NCS1) in chemotherapy-induced neuropathy has been described for taxane treatment, where its expression decreases soon after administration and remains low post-chemotherapy." (PMID 40595283, 2025). "NCS-1/InsP3R interaction is also considered to mediate neuropathy, as paclitaxel (taxol), a chemotherapeutic agent used for the treatment of solid cancers, modulates the expression/function of NCS-1, and hence InsP3R1-mediated Ca2+ signaling." (PMID 30886571, 2019). "Mice treated with paclitaxel that are administered calpain inhibitors show reduced signs of axonal degeneration in sensory neurons and improved clinical measures of neuropathy One of the targets of calpain during paclitaxel-induced peripheral neuropathy is neuronal calcium sensor-1 (NCS-1)." (PMID 28912674, 2017). "Lithium’s modulation of NCS1 function is dose-dependent, and our study confirms that in MMAE-induced neuropathy, lithium dosage is critical." (PMID 40595283, 2025). "NCS1 and TRPA1 have a role not only in cancer but also in the development of neuropathy, a reason to carry out tests in neuronal models such as SH-SY5Y cells." (PMID 38564162, 2024).
Wolfram syndrome (5 papers, 2019 to 2025). Wolfram syndrome (WS) also known as DIDMOAD, is a neurodegenerative disorder characterized by type I diabetes mellitus (DM), diabetes insipidus (DI), sensorineural deafness (D), bilateral optical atrophy (OA) and neurological signs. "In fibroblasts from patients with Wolfram syndrome, the expression of NCS1 in MAMs was reduced, whereas overexpression of NCS1 or activation of σ1 receptors restored the diminished Ca2+ transfer and its functional consequences." (PMID 40955171, 2025). "Delprat and colleagues overexpressed NCS1 by a gene therapy strategy in a Wolfram syndrome zebrafish model that led to an attenuation the locomotor and metabolic symptoms." (PMID 36320410, 2022). "Specifically, preclinical models that may show benefits by targeting NCS1 include Fragile X syndrome, Alzheimer’s disease, and Wolfram syndrome." (PMID 36206298, 2022). "This phenotype could be rescued by NCS-1 overexpression, similar as described for respective mitochondrial dysfunction in fibroblasts from Wolfram Syndrome patients." (PMID 31827421, 2019). "Also, the wfs1ab knockout fish model of the Wolfram syndrome phenotype was studied for locomotion (motor response to light–dark sequence) and mitochondrial function (oxygen consumption rate with the Agilent Seahorse XF Cell Mito Stress test) at 5 days post-injection of murine Ncs1 mRNA." (PMID 37446400, 2023).
Alzheimer disease (4 papers, 2020 to 2025). A progressive, neurodegenerative disease characterized by loss of function and death of nerve cells in several areas of the brain leading to loss of cognitive function such as memory and language. "Recently, the NCS-1 expression level was found to be dysregulated in patients with Alzheimer’s disease." (PMID 31973069, 2020).
autism (4 papers, 2010 to 2021). Persistent deficits in social interaction and communication and interaction as well as a markedly restricted repertoire of activity and interest as well as repetitive patterns of behavior. "Loss of this tail has a dramatic effect on the dynamics of NCS-1, an effect which is also observed with an autism-related mutation in NCS-1 (R102Q)." (PMID 32936312, 2021). "Defective NCS-1 can be deleterious to cells and has been linked to serious neuronal disorders like autism." (PMID 30618617, 2018). "A similar loss in resonances from residues in the J helix was seen in NCS-1 bearing an autism-related mutation (R102Q) that was predicted to disrupt hydrogen binding between helix F and helix J." (PMID 22114693, 2011). "To test the prediction that movement of the C-terminal region is important for ligand interactions, we examined binding of D2SR peptide to the autism-related R102Q mutant form of NCS-1." (PMID 22114693, 2011).
depression (4 papers, 2019 to 2022). "Ncs-1−/−-mice exhibit behavioral amphetamine sensitization, suggesting that NCS-1 plays a role in a type of long-term depression and AMPA receptor endocytosis in the paranasal cortex." (PMID 36555318, 2022).
Cognitive impairment (3 papers, 2015 to 2025). Abnormal cognition is characterized by deficits in thinking, reasoning, or remembering. "To evaluate whether NCS1 is involved in MMAE-induced cognitive impairment, we measured its expression via RT-PCR in treated mouse brains." (PMID 40595283, 2025). "Prophylactic treatment of rodents with lithium inhibits the NCS1-InsP3R interaction and ameliorates paclitaxel-induced polyneuropathy and cognitive impairment, which is in part supported by limited retrospective clinical data in patients treated with lithium carbonate at the time of chemotherapy." (PMID 36035422, 2022). "Therapeutically, finding novel molecular targets, such as NCS-1, to ameliorate cognitive deficits in these disorders may be possible by focusing on the mechanisms coupling self-directed exploration to efficient learning." (PMID 26639399, 2015).
cardiac hypertrophy (2 papers, 2015 to 2019). "We have previously demonstrated that phenylephrine-induced cardiac hypertrophy was significantly attenuated in NCS-1 KO hearts concomitant with a reduced activation of both calcineurin/NFAT and CaMKII/HDAC pathways." (PMID 25897502, 2015). "We had previously reported that IP3R-mediated cardiac hypertrophy is regulated by a Ca2+ binding protein, neuronal Ca2+ sensor-1 (NCS-1)." (PMID 25897502, 2015). "Therefore, NCS-1-dependent nuclear [Ca2+] regulation may also be involved in cardiac hypertrophy through these pathways." (PMID 25897502, 2015).
cocaine addiction (2 papers, 2016 to 2017). "Single nucleotide polymorphisms in NCS-1 are associated with cocaine addiction in African Americans and expression levels of NCS-1 correlate with addiction-like behaviors in rats." (PMID 27575489, 2016).
diabetes type 2 (2 papers, 2019). "We propose that NCS-1 plays an important role in adipocyte function and that NCS-1 deficiency gives rise to obesity and diabetes type 2 in adult mice." (PMID 31001084, 2019). "It demonstrates that NCS-1 deficiency leads to diabetes type 2 and to behavioral phenotypes reminiscent of psychiatric disorders." (PMID 31001084, 2019). "The here studied NCS-1 KO mice showed decreased motivation, associated with lower dopamine release in the nucleus accumbens, and they are prone to gain weight and develop type 2 diabetes." (PMID 31827421, 2019). "Our data indicate that NCS-1 plays an important role in adipocyte function and that NCS-1 deficiency yields obesity and diabetes type 2 in adult NCS-1−/− mice." (PMID 31001084, 2019). "The observed effects of NCS-1 deficiency on IR concentration and on adipokinine secretion in combination with the observed hyperinsulinemia, hyperglycemia and obesity strongly suggest that the phenotype of NCS-1−/− mice resembles type 2 diabetes." (PMID 31001084, 2019). "NCS-1−/− mice, therefore, exhibit a genetic link for diabetes type 2 and mood-related behaviors." (PMID 31001084, 2019). "Therefore, we propose NCS-1 as a novel player in the development of type 2 diabetes." (PMID 31001084, 2019). "Adult NCS-1−/− mice are obese, especially when fed a high-fat diet (HFD), are hyperglycemic and hyperinsulinemic and thus develop a diabetes type 2 phenotype." (PMID 31001084, 2019).
fragile X syndrome (2 papers, 2022). A genetic syndrome caused by mutations in the FMR1 gene which is responsible for the expression of the fragile X mental retardation 1 protein. "While the use of NCS1 is currently explored in other indications such as cancer and fragile X syndrome, developing therapies with NCS1 as a target in the context of WS is new, and only cell-based studies have been performed so far." (PMID 36320410, 2022).
liver cancer (2 papers, 2022 to 2023). An epithelial or non-epithelial malignant neoplasm that arises from the liver. "The outcomes indicated that NCS1 had hypermethylation in LIHC (Liver Cancer) (p value = 1.09 × 10−8), BRCA (p value = 1.09 × 10−8), COAD (Colon Cancer) (p value = 5.69 × 10−8), and KIRC (p value < 1 × 10−12)." (PMID 37893139, 2023).